RRM2B (ribonucleotide reductase regulatory TP53 inducible subunit M2B)
Description:
Supplies deoxyribonucleotides for DNA repair in cells arrested at G1 or G2. Contains an iron-tyrosyl free radical center required for catalysis. Forms an active ribonucleotide reductase (RNR) complex with RRM1 which is expressed both in resting and proliferating cells in response to DNA damage.
Synonyms: p53R2; MTDPS8A; MTDPS8B; RCDFRD
Tractability: Small molecule: a drug acting on it is in phase 2 or 3 trials; it has a binding pocket of medium quality; it belongs to a druggable protein family. PROTAC: ubiquitination databases record sites on it; its protein half-life has been measured.
Gene: Protein-coding gene on chromosome 8 (102,204,502 to 102,239,382, reverse strand). Ensembl gene ENSG00000048392.
Subcellular location: Cytoplasm; Nucleus
Subcellular location (Human Protein Atlas): Nucleoplasm; Cytosol
Pathways (Reactome):
Metabolism: Interconversion of nucleotide di- and triphosphates
Gene Ontology:
Molecular function: identical protein binding; protein binding; ribonucleoside-diphosphate reductase activity, thioredoxin disulfide as acceptor; oxidoreductase activity
Biological process: 2'-deoxyribonucleotide biosynthetic process; DNA repair; mitochondrial DNA replication; positive regulation of G0 to G1 transition; positive regulation of G2/M transition of mitotic cell cycle; ribonucleoside diphosphate metabolic process; deoxyribonucleotide biosynthetic process; DNA synthesis involved in DNA repair; positive regulation of mitotic cell cycle phase transition; response to amine
Cellular component: cytosol; nucleoplasm; cytoplasm; mitochondrion; nucleus
Genetic constraint (gnomAD): Loss-of-function variants: 11 observed, 26.45 expected, observed/expected ratio (o/e) 0.42, 90% interval 0.26 to 0.69. The upper end of that interval is the gene's LOEUF score, 0.69, which puts it in group 2 of 6, group 1 being the genes least tolerant of losing a copy. Missense variants: 199 observed, 250.71 expected, observed/expected ratio (o/e) 0.79, 90% interval 0.71 to 0.89. Synonymous variants: 74 observed, 81.96 expected, observed/expected ratio (o/e) 0.9, 90% interval 0.75 to 1.1.
Homologues: Orthologues: macaque RRM2B (98% identical), chimpanzee RRM2B (97% identical), dog RRM2B (96% identical), pig RRM2B (95% identical), rat Rrm2b (94% identical), mouse Rrm2b (93% identical), guinea pig RRM2B (91% identical), rabbit RRM2B (82% identical), tropical clawed frog rrm2b (82% identical), zebrafish rrm2b (74% identical), Drosophila melanogaster RnrS (72% identical), Caenorhabditis elegans rnr-2 (64% identical). Paralogues in human: RRM2 (78% identical).
Diseases named in the same sentence as RRM2B in open-access papers:
RRM2B is named in the same sentence as 101 diseases in open-access papers, as found by Europe PMC text mining. Sharing a sentence is not in itself a finding about the gene and the disease. The quoted sentences say what the papers report.
mitochondrial DNA depletion syndrome (14 papers, 2009 to 2025). The mitochondrial DNA (mtDNA) depletion syndrome (MDS) is a clinically heterogeneous group of mitochondrial disorders characterized by a reduction of the mtDNA copy number in affected tissues without mutations or rearrangements in the mtDNA. "As mtDNA depletion syndromes are tissue specific, with pathogenic RRM2B variants primarily affecting the CNS and skeletal muscle, we assessed mtDNA copy number in different tissues of 5 dpf rrm2b larvae." (PMID 40211788, 2025). "Inactivating variants in RRM2B, encoding part of Ribonucleotide Reductase (RR) causes a severe mtDNA depletion syndrome that is fatal in the neonatal period." (PMID 34918187, 2022). "The disorder has also been misdiagnosed as other mitochondrial DNA depletion syndromes such as POLG or RRM2B mutations or other mitochondrial diseases, including Kearns-Sayre syndrome and chronic progressive external ophthalmoplegia." (PMID 32914088, 2020). "Dysfunction of RRM2B was first reported in mitochondrial DNA depletion syndrome which caused early fatality in children." (PMID 30774750, 2019). "Phenotypes resembling MNGIE may be seen in patients with other mitochondrial DNA depletion syndromes including POLG or RRM2B mutations and Kearns-Sayre syndrome." (PMID 30627136, 2018). "Thirty-three individuals have been extensively genotyped and harbour RRM2B gene mutations characterized by either autosomal-recessive mitochondrial DNA depletion syndrome or recessive and dominant mutations that cause the accumulation of multiple mitochondrial DNA deletions." (PMID 23107649, 2012). "To date, mutations in just four of these genes – POLG, PEO1, RRM2B and recently TK2 – have been described as causes of both infantile mtDNA depletion syndromes and adult-onset, multiple mtDNA deletion disorders." (PMID 22508010, 2012). "However, the patient’s phenotype was consistent with autosomal recessive infantile-onset RRM2B-related mitochondrial DNA depletion syndrome." (PMID 37784170, 2023).
breast carcinoma (9 papers, 2012 to 2022). "Cases with CNV alterations (all CNV gain, other than 1 CNV loss liver cancer case and 1 CNV loss breast cancer case) in RRM2B were associated with decreased OS in liver, breast, and prostate carcinoma, and ovarian serous cystadenocarcinoma." (PMID 27004405, 2016). "In total, 11 DNA repair genes (UBE2A, RBBP8,RAD50, FAAP20, RPA3, ENDOV, DDB2, UBE2V2,MRE11, RRM2B, andPARP3) were preserved as prognostic genes to estimate risk score, which was applied to establish the prognostic model and stratified breast cancer patients into two groups with high or low risk." (PMID 36713553, 2022). "Based on the distinct tumor signatures observed in RRM2B-amplified breast cancers, we next tested whether RRM2B-amplifications associate with clinical outcomes." (PMID 33868369, 2021). "Notably, RRM2B-amplified cancers are characterized by mutation signatures of defective DNA repair and oxidative stress, and at least RRM2B-amplified breast cancers are associated with poor clinical outcome." (PMID 33868369, 2021). "As an unfavorable factor indicated in the present study, we suggested intensive research on the role of RRM2B in breast cancer." (PMID 35574387, 2022). "The hazard ratio of other six genes (FAAP20, RRM2B, UBE2A,RAD50,MRE11, and RPA3) was >1, regarded as risk factors in developing breast cancer." (PMID 36713553, 2022). "A total of 11 DNA repair genes, namely, UBE2A, RBBP8,RAD50, FAAP20, RPA3, ENDOV, DDB2, UBE2V2,MRE11, RRM2B, andPARP3, were involved in the prognostic model for breast cancer patients." (PMID 36713553, 2022). "In breast cancer, multiple genes localized in the 8q12.1–8q24.23 interval were found to be amplified, including RRM2B." (PMID 33868369, 2021). "There is almost no copy number variation (CNV) of RRM1 and RRM2 genes in common types of cancers, whereas RRM2B displays CNV gain in more than 3% of breast cancers, liver cancers, stomach cancers and urinary tract cancers." (PMID 31637211, 2019). "The relatively frequent aberrations observed in this study imply that RRM1 and RRM2B are capable of contributing to breast cancer development." (PMID 24215511, 2013). "Analysis of the most common breast cancer subtype indicated that RRM2B amplifications may independently impact clinical outcomes in these cancers." (PMID 33868369, 2021). "The analysis of clinical outcomes in breast cancer revealed that based on the cancer subtype, co-alteration of RRM2B with MYC, or alone may significantly impact patient outcomes." (PMID 33868369, 2021). "This study demonstrated the existence of both deletions and amplifications of RRM1 and RRM2B in primary breast tumor samples, to our knowledge unprecedented in human tumor tissue but in agreement with the frequently observed somatic changes in the genome of breast cancer cell lines." (PMID 24215511, 2013). "From the results, we found that mRNA expressions of SLC19A1, CYC1, RRM2B, and OCRL were clearly elevated in breast cancer, while RPS14 expression was considerably decreased." (PMID 35574387, 2022). "And for the survival analyses of OS, high expressions of SLC19A1, CYC1, RRM2B, and OCRL and downregulation of RPS14 were significantly related to more unfavorable OS in breast cancer, which further confirmed the validity of selected genes." (PMID 35574387, 2022). "EIF3E, another 8q-protein in the RRM2B network, interacts with ATM and BRCA1 for the execution of DNA damage response and EIF3E alterations have been previously observed in breast cancer." (PMID 33868369, 2021). "The expression level of DDB2, RPA3,RAD50, RRM2B, and UBE2A was higher in breast cancer tissues with lymph node metastasis compared with breast cancer tissues without lymph node metastasis, which was estimated by the distribution of their expression level between N0 and N1–N3 stages." (PMID 36713553, 2022).
breast carcinoma (continued). "By performing the LASSO Cox regression analysis with 9 candidate genes in breast cancer patients of TCGA-BRCA training dataset, 5 pivotal genes were unearthed to establish the prognostic signature, Lactate Metabolism Index, namely LMI, including RPS14, SLC19A1, CYC1, RRM2B, OCRL." (PMID 35574387, 2022). "We observed that several genes, specifically RRM2B, HNRNPU, Dux4, SYNCRYP, and WISP-1 are regulated in a similar fashion in tubular epithelial cells as in breast cancer cells whereas remaining genes have not shown similar regulation (data not shown)." (PMID 29254187, 2017).
colorectal cancer (9 papers, 2013 to 2026). A primary or metastatic malignant neoplasm that affects the colon or rectum. "For example, it has been reported that RRM2B expression was reversely associated with tumor metastasis and was correlated with a better survival in colorectal cancer patients." (PMID 31637211, 2019). "The 8q region also contains genes (RRM2B, NOV, RAD21) associated with the metastatic process, which is well described in studies on the progression of colorectal cancer." (PMID 40943426, 2025). "RRM2B intriguingly exerts opposite activity to RRM2 and its expression associates with a better survival of colorectal cancer patients." (PMID 27733154, 2016). "Published results indicate that PPP2R5E, PES1, RRM2B, GLRX, and CRKL are important in the prognosis and development of colorectal cancer." (PMID 37895091, 2023).
lung carcinoma (9 papers, 2013 to 2022). "To further characterize the expression pattern of RRM1, RRM2, and RRM2B in different pathological types and stages of cancer, we chosen lung cancer as a representative cancer type as it is the leading cause of cancer death all over the world." (PMID 31637211, 2019). "In contrast, no study showed down-regulated expression of RRM1 (0 of 19) or RRM2 (0 of 19) in all subtypes of lung cancer, 22.2% (2 in 9) of the Oncomine studies demonstrated a down-regulated RRM2B expression in cases of LUSC and LCLC." (PMID 31637211, 2019). "The cancer tissue microarray data also demonstrated a strong correlation between the co-expression of FOXO3 plus RRM2B and increased disease survival and reduced recurrence or metastasis in lung cancer patients." (PMID 24947616, 2014). "Although these genes were previously reported in some cancer types, their specific role in lung cancer is unclarified except for ATP8A2 and RRM2B." (PMID 34760888, 2021). "Moreover, we obtained translational IHC data by using a tissue microarray prepared from samples of lung-cancer patients, and the results indicated that the expression of FOXO3 and RRM2B can be used as a predictive biomarker in future cancer diagnostics." (PMID 24947616, 2014).
Kearns-Sayre syndrome (6 papers, 2011 to 2025). Kearns-Sayre syndrome (KSS) is a mitochondrial disease characterized by progressive external ophthalmoplegia (PEO), pigmentary retinitis and an onset before the age of 20 years. "Kearns-Sayre syndrome, a rare disease belonging to progressive external ophthalmoplegia (PEO), is caused by heterozygous mutation in RRM2B." (PMID 35906243, 2022). "We can also mention Kearns-Sayre syndrome (KSS) as one of the rare phenotypes that may occur due to mutations in the RRM2B gene." (PMID 32775440, 2020). "In the screening of RRM2B variants in 50 mitochondrial disease patients without causative variants in POLG1 and C10orf2, one Kearns-Sayre syndrome (MIM 530000) patient who carried two different novel missense variants and one PEO patient who carried an in-frame deletion were identified." (PMID 21951382, 2011).
esophageal squamous cell carcinoma (5 papers, 2015 to 2022). Esophageal squamous cell carcinoma (ESCC) is a type of esophageal carcinoma (EC) that can affect any part of the esophagus, but is usually located in the upper or middle third. "Conversely, RRM2B expression has been previously reported to be positively related to the development of esophageal squamous cell carcinoma." (PMID 31637211, 2019).
liver cancer (5 papers, 2016 to 2023). An epithelial or non-epithelial malignant neoplasm that arises from the liver. "In the current study, we also found that the expression of RRM2B was increased in liver cancer and related cell lines, contradictory to a previous study." (PMID 36713030, 2023). "Time-dependent ROC curves were adopted to compare the prognostic accuracy of RRM1, RRM2, and RRM2B in predicting the prognosis of liver cancer." (PMID 36713030, 2023). "The expressions of RRM1, RRM2, and RRM2B were remarkably upregulated among liver cancer tissue both in mRNA and protein levels." (PMID 36713030, 2023). "Using the GeneMANIA database, we also identified RRM1-, RRM2-, and RRM2B-related molecules, which were also involved with liver cancer." (PMID 36713030, 2023). "Using cancer cases from TCGA, we observed that RRM2B is frequently amplified, with the highest percentage observed in ovarian, breast, bladder, and liver cancers (21.54–14.5%), and a lower rate of amplifications in multiple other cancers (14–0.6%)." (PMID 33868369, 2021). "In TCGA cohort, the expression of RRM1, RRM2, and RRM2B was significantly higher in liver cancer." (PMID 36713030, 2023). "The ROC curve analysis demonstrated that the discriminative abilities of liver cancer for RRM1, RRM2, and RRM2B were 0.903 (95% CI: 0.873-0.933), 0.961 (95% CI: 0.939-0.984) and 0.767 (95% CI: 0.715-0.820), respectively." (PMID 36713030, 2023). "To determine the involvement of RRM2 and RRM2B in HB cell drug response, we treated tdT, RRM2OE and RRM2BOE HepG2 cells with six common liver cancer drugs and the two RRM2 inhibitors triapine and MK1775." (PMID 36882565, 2023). "To assess the potential impact of the RR subunits on chemotherapy of liver cancer, we evaluated the correlations between the expression levels of RRM1, RRM2, and RRM2B and multiple drugs." (PMID 36713030, 2023).
colon cancer (3 papers, 2013 to 2017). "An association between RRM2B expression and increased survival has been noticed in lung and colon cancer, whereas an association with poor prognosis has been observed in esophageal cancer patients." (PMID 24215511, 2013).
hepatocellular carcinoma (3 papers, 2019 to 2022). A malignant tumor that arises from hepatocytes. "RRM2B expression was also shown to be reversely associated with intrahepatic metastasis in hepatocellular carcinomas." (PMID 31637211, 2019). "MiR-942 targeted RRM2B to affect cell growth in hepatocellular carcinoma and regulated BARX2 to modulate NSCLC cell progression." (PMID 35230201, 2022).
lactic acidosis (3 papers, 2013 to 2025). Metabolic acidosis characterized by the accumulation of lactate in the body. "We report a case of an infant with myopathy, deafness, peripheral neuropathy, nephrocalcinosis, proximal renal tubulopathy, moderate lactic acidosis, and a novel mutation of the RRM2B gene." (PMID 24382854, 2013). "In patients with mitochondrial depletion syndrome, a novel mutation of RRM2B was diagnosed, which presents with early muscular hypotonia, renal tubulopathy, diarrhea, lactic acidosis, and rapid progressive lethal course." (PMID 24382854, 2013). "In this report, we review a case of an infant with muscular hypotonia, myopathy, peripheral neuropathy, deafness, nephrocalcinosis, proximal renal tubulopathy, moderate lactic acidosis, and a novel mutation of the RRM2B gene." (PMID 24382854, 2013). "As lactic acidosis is often seen in patients with RRM2B-related disease, and in many other mitochondrial diseases, we looked to establish if lactate levels change in 7 dpf rrm2b larvae." (PMID 40211788, 2025).
Mitochondrial myopathy (3 papers, 2017 to 2025). "We found that loss of Rrm2b in the myofibers upregulated the expression of Fgf21, which is a local and systemic messenger in mice and humans with mitochondrial myopathy through autocrine and paracrine mechanisms." (PMID 35906243, 2022). "Mutations in mitochondrial genes, such as MT-ATP6, and nuclear genes, such as MGME1 [MIM:615076] and RRM2B [MIM:604712], which are essential for mitochondrial function, can cause mitochondrial myopathy [MIM:500009], sometimes accompanied by ptosis." (PMID 40410591, 2025). "We explored the importance of Rrm2b in skeletal muscle repair and regeneration and identified the Rrm2b tissue-specific knockout mouse model as a potential disease model for studying mitochondrial myopathy." (PMID 35906243, 2022). "Consequently, the Rrm2b smKO mouse model can be used to study the progression of mitochondrial myopathy." (PMID 35906243, 2022). "Using a genetic approach, we identified a novel role of Rrm2b in muscle homeostasis, and animals with defective Rrm2b expression could serve as a disease model for investigating mitochondrial myopathy in mammals." (PMID 35906243, 2022).
mitochondrial neurogastrointestinal encephalopathy (3 papers, 2011 to 2019). "The first reported adult-onset case was in a 30-year-old female with mitochondrial neurogastrointestinal encephalopathy who harboured compound heterozygous missense mutations in RRM2B and mitochondrial DNA depletion." (PMID 23107649, 2012).
ovarian carcinoma (3 papers, 2012 to 2021). A malignant neoplasm originating from the surface ovarian epithelium. "For this analysis, we selected breast and ovarian cancer studies as they had the highest frequency of RRM2B alterations." (PMID 33868369, 2021).
ptosis (3 papers, 2012 to 2025). The drooping of the upper eyelid. "Evaluation of the clinical features of all 31 adult patients harbouring pathogenic RRM2B mutations showed that PEO was universal and frequently associated with ptosis (28 patients)." (PMID 23107649, 2012).